SERTM1 (serine rich and transmembrane domain containing 1)
Synonyms: C13orf36
Tractability: Antibody: UniProt predicts a signal peptide or a membrane-spanning region.
Gene: Protein-coding gene on chromosome 13 (36,673,881 to 36,697,839, forward strand). Ensembl gene ENSG00000180440.
Subcellular location: Membrane
Subcellular location (Human Protein Atlas): Vesicles
Gene Ontology:
Molecular function: protein binding
Cellular component: membrane
Genetic constraint (gnomAD): Loss-of-function variants: 1 observed, 5.56 expected, observed/expected ratio (o/e) 0.18, 90% interval 0.063 to 0.85. That is too few expected variants to judge how well the gene tolerates losing a copy. Missense variants: 91 observed, 129.35 expected, observed/expected ratio (o/e) 0.7, 90% interval 0.59 to 0.84. Synonymous variants: 52 observed, 57.91 expected, observed/expected ratio (o/e) 0.9, 90% interval 0.72 to 1.13.
Homologues: Orthologues: chimpanzee SERTM1 (100% identical), macaque SERTM1 (98% identical), dog SERTM1 (97% identical), mouse Sertm1 (96% identical), rat Sertm1 (96% identical), pig SERTM1 (95% identical), rabbit SERTM1 (94% identical), tropical clawed frog sertm1 (81% identical).
Diseases named in the same sentence as SERTM1 in open-access papers:
SERTM1 is named in the same sentence as 5 diseases in open-access papers, as found by Europe PMC text mining. Sharing a sentence is not in itself a finding about the gene and the disease. The quoted sentences say what the papers report.
glioma (1 paper, 2021). A benign or malignant brain and spinal cord tumor that arises from glial cells (astrocytes, oligodendrocytes, ependymal cells). "The expression level of these candidate genes in a public database (GEPIA) was searched, and only two of them (serine rich and transmembrane domain containing 1 (SERTM1), and NRXN3) were downregulated in gliomas." (PMID 34035217, 2021).
psoriasis (1 paper, 2018). An autoimmune condition characterized by red, well-delineated plaques with silvery scales that are usually on the extensor surfaces and scalp. "Top up-regulated DEGs in CP vs C include previously identified psoriasis-associated genes such as IL36A/G, SPRR2A/B/F, SERPINB4, S100A7A, S100A9, and IL17F while top down-regulated DEGs include SERTM1, IL6, and ADAMTS16." (PMID 30054515, 2018).
SERTM1 also shares sentences with these, for which no sentence is quoted: Abdominal obesity (1 paper); lung adenocarcinoma (1); Obesity (1).